ARID1A (AT-rich interaction domain 1A)
Diseases named in the same sentence as ARID1A in open-access papers (continued):
Sharing a sentence is not in itself a finding about the gene and the disease.
cancer (continued). "Patients with decreased ARID1A have a poor prognosis, and the mutation of ARID1A promotes metastases of cancers." (PMID 37238613, 2023). "ARID1A-deficient cancer cells demonstrate increased sensitivity to treatment with small molecule inhibitors of the PI3K/AKT pathway." (PMID 37711591, 2023). "The mutation spectrum of ARID1A, which is currently the most prevalent mutated gene in all cancers, is also of interest." (PMID 36600315, 2023). "Components of SWI/SNF are mutated in 20% of all human cancers, of which mutations in AT-rich binding domain protein 1A (ARID1A) are the most common." (PMID 38275587, 2023). "ARID1A is mutated in 9% of all cancers based on a survey of 24 whole exome studies across 18 different cancer types, followed by PBRM1 (4%) and SMARCA4 (3%)." (PMID 38275587, 2023). "The effect of ARID1A mutation can be compared with another commonly mutated gene in human cancers, phosphatase and tensin homolog (PTEN)." (PMID 36910637, 2023). "ARID1A mutation has been explored as a predictor of immunotherapeutic responsiveness in metastatic urothelial carcinoma and pan-cancer analysis." (PMID 36369379, 2023). "The results of our study provide a new strategy for using PARPi alone or in combination with DNA-damaging agents (radio or chemotherapy) to treat ARID1A-mutated cancers, as well as many other PI3K/Akt1-induced cancers." (PMID 36910637, 2023). "Other preclinical studies have associated ARID1A-mutant cancers with an increased number of TIL, higher PD-L1 expression, and the benefit from ICI treatment." (PMID 37446319, 2023). "ARID1B, as a component of a subset of cBAF complexes, is a homolog of ARID1A that promotes a compensatory pathway in the event of loss of ARID1A in some cancers." (PMID 36844227, 2023). "In ARID1A-deficient cancers, at least one functional ARID1B allele is maintained, and loss of ARID1B leads to destabilization of the SWI/SNF complex and subsequent impaired cell proliferation." (PMID 36980292, 2023). "We will summarize the recent advances in targeting ARID1A-deficient cancers by harnessing immune-metabolic vulnerability elicited by ARID1A deficiency to stimulate antitumor immune response, and ultimately, to improve patient outcome." (PMID 36980292, 2023). "The high frequency of ARID1A mutations among different cancer types, made this gene a very appealing research object for target therapy investigations." (PMID 36890819, 2023). "ARID1A has been identified as a tumor suppressor gene with one of the highest mutation rates across different cancer types." (PMID 36910637, 2023). "While ARID1A mutations are well‐studied, the role of ARID1B in cancer and its potential as a therapeutic target in ARID1A‐deficient cancers are areas of ongoing research." (PMID 38041544, 2023). "Mutations in the ARID1A gene can lead to disruptions in the regulation of genes involved in cell growth, differentiation, and DNA repair, contributing to the development of cancer." (PMID 37958970, 2023). "Accumulating evidence has demonstrated promising preclinical and clinical results of combinational therapy to target cancers harboring ARID1A mutations." (PMID 36980292, 2023). "Other cancers associated with Other cancers associated with mutations that lead to loss-of-function in the ARID1A gene are endometrial cancers, gastric cancers, bladder cancers, hepatocellular cancers, melanomas, colon cancers, and lung cancers." (PMID 37958970, 2023). "Comparably, cancer cells with ARID1A deficiency are also susceptible to the inhibition of ATR activity." (PMID 37371564, 2023). "The most frequently mutated gene of the complex is ARID1A, which is altered in about 10% of human cancers." (PMID 36890819, 2023). "A comprehensive understanding of the ARID1A-DUSP4-MAPK axis would be fundamental for designing an effective treatment or ARID1A-mutated cancers." (PMID 38071325, 2023).
cancer (continued). "Promoter hypermethylation has been linked to decreased ARID1A mRNA expression in various cancer types, including invasive breast cancers and cholangiocarcinoma." (PMID 38041544, 2023). "Previous research reported that loss of intact BAF, and especially the functional loss of ARID1A, endows cells with cancerous functions and leads to a poor prognosis for multiple types of cancer." (PMID 36869329, 2023). "For instance, given the importance of SWI/SNF to HR, PARPi therapy is currently investigated in clinical trials of ARID1A mutated cancers." (PMID 37470997, 2023). "Recent findings that ARID1A deficiency is related to sensitivity to ICB therapy in multiple cancer types have paved the way of harnessing ARID1A as a novel target for cancer immunotherapy." (PMID 36980292, 2023). "Along the same lines, in a series of 42 OCCC samples, somatic mutations of PIK3CA were detected in 40% of the carcinomas and the majority (71%) of these were ARID1A-deficient tumors." (PMID 37627318, 2023). "ARID1A-deficient cancer cells appear to present a relatively low profile of SLC7A11 because the SWI/SNF complex recruitment to the promoter of SLC7A11 is dramatically reduced, which results in the impediment of GSH synthesis." (PMID 35884471, 2022). "Patients with ARID1A mutations had a significantly greater number of mutations in the cancer‐associated sequenced by CANCERPLEX." (PMID 34042312, 2022). "The ARID1A gene mutation is detected in some types of cancer in the ovary, stomach, or bile tract and is of interest as a target for anti-cancer drug development." (PMID 34811710, 2022). "While haploinsufficiency of ARID1A can drive cancer formation, upon its loss, the paralogous subunit, ARID1B, promotes cBAF binding to pro-tumorigenic loci." (PMID 35323214, 2022). "In human cancers, ARID1A shows predominantly nonsense truncating point mutations, resulting in lower protein levels and overall inactivation." (PMID 35852858, 2022). "Loss-of-function ARID1A-mutant cancers are sensitive to ARID1B KO, causing destabilization of the SWI/SNF chromatin remodeling complex." (PMID 36040810, 2022). "ARID1A mutations negatively impact DNA damage repair in cancer cells and while their role in regulating sensitivity to checkpoint inhibitors is unclear, they have been also shown to sensitize cancer cells to PARP inhibition as well as to EZH2 inhibition." (PMID 35664801, 2022). "The specific molecular mechanisms by which ARID1A mutations contribute to cancer are likely to be complex and remain an area of active investigation." (PMID 36117191, 2022). "Alterations in genes encoding subunits of SWI/SNF complexes are of significant importance in cancer, being discerned in ~20% of human malignancies, with ARID1A loss-of-function alterations found in ~6% of solid tumor tissue samples." (PMID 36077815, 2022). "The gender and cancer topography (T) categorization of HCC were linked to increased ARID1A expression." (PMID 35028302, 2022). "In fact, ATR inhibitors have been reported to act in a synthetic lethal way in ARID1A-deficient cancer." (PMID 36123603, 2022). "Further, it has been described that ARID1A deficient tumors have a higher level of PD-L1 expression compared to WT-correlates in a variety of different cancer subtypes." (PMID 35565222, 2022). "As a result, the inhibition of HDAC6 activity represents an exciting therapeutic possibility in high‐grade/stage, invasive or metastatic EC harbouring ARID1A mutations, since metastasis is the main cause of death in patients with cancer." (PMID 35167193, 2022). "Further prospective clinical trials are necessary to evaluate PARPi efficacy in ARID1A mutated cancers, particularly given its relatively high frequency across all tumor types." (PMID 35626165, 2022). "The Cancer cohorts section also reveals ARID1A mutations in multiple cancer subtypes, which is consistent with the Literature section." (PMID 36035123, 2022).
cancer (continued). "We will also provide our insights into the promises and challenges in developing therapeutic strategies to treat cancers with ARID1A mutations." (PMID 36123603, 2022). "ARID1B is essential for the survival of ARID1A mutated cancer cells, by supplying residual BAF complex activities to maintain chromatin accessibility at enhancers and regulate RNA polymerase II dynamics." (PMID 35715442, 2022). "Among the family of the SWI/SNF genes, AT-rich interaction domain 1A (ARID1A) is a common-mutated gene in human cancers, which contributes to the binding of protein and DNA." (PMID 35421925, 2022). "We also discuss strategies to harness synthetic lethal mechanisms for future therapeutics against ARID1A-mutated cancers." (PMID 36123603, 2022). "Currently, research related to ARID1A deficiency in cancer has led to the identification of DSB repair pathways that are compromised, increasing thus the vulnerability of cancer cell lines to the applied treatment modalities." (PMID 36249060, 2022). "ARID1A is considered a cancer-inhibiting gene that encodes ARID1A protein belonging to the chromatin remodeling complex." (PMID 36612107, 2022). "Mutations in the ARID1A gene are frequently nonsense, which is consistent with a suppressor role for ARID1A in various cancers." (PMID 36420658, 2022). "In particular, ARID1A is frequently mutated and/or lost in various cancers, including ovarian, breast, and hepatic cancers 7-12." (PMID 35069887, 2022). "As several ATR inhibitors have entered into clinical studies, targeting ATR holds promise to treat ARID1A mutated cancers." (PMID 36123603, 2022). "With the exception of CDKN2A, which carried few mutations overall, all genes carried high levels of cancer driver mutations ranging from 40% in ARID1A to 85% in KRAS." (PMID 36311816, 2022). "For example, cancer cells defective in BRG1 are usually sensitive to the removal of BRM, whereas cancer cells with ARID1A mutations are vulnerable to the loss of ARID1B13–17." (PMID 36335117, 2022). "Downregulation of the ARID1A gene in cancers is attributed to genomic deletion, DNA mutation, DNA methylation, and microRNA-mediated inhibition." (PMID 35611248, 2022). "In the genetic field, in particular, mutations that activate PIK3CA associated with the loss of ARID1A expression appear to be necessary for cancer development." (PMID 35328379, 2022). "ARID1A mutations have also been studied for their potential role as biomarkers for predicting clinical outcomes in cancer patients." (PMID 36123603, 2022). "Another study by Fukumoto observed that combined treatments with the HDAC6 inhibitor and anti-PD-L1 in ARID1A-mutated cancers showed efficient antitumor effects caused by improved cytotoxic T-cell activity." (PMID 36361605, 2022). "This feature provides a rationale for targeting both stress kinases (ATM/ATR) in ARID1A-deficient cancers." (PMID 36123603, 2022). "A TCGA database search revealed that the R1989* nonsense mutation in the DUF3518 domain is a hotspot mutation of ARID1A across cancers." (PMID 36371186, 2022). "ARID1A is mutated in ovarian clear cell, endometroid, and uterine endometroid carcinomas, among other cancer types." (PMID 36605718, 2022). "Among the chromatin remodeling genes, ARID1A shows one of the highest mutation rates across different cancer types in people, and it is one of the most frequently inactivated genes in CCA." (PMID 35070505, 2022).
cancer (continued). "Among the six SWI/SNF genes, ARID1A and SMARCB1 were, respectively, the most and least frequently mutated genes in the majority of the cancer types (ARID1A, 10.7%; SMARCA4, 6.0%; ARID1B, 4.7%; ARID2, 4.0%; PBRM1, 3.5%; SMARCB1, 1.3%)." (PMID 36371186, 2022). "We observed the suppression of the cellular senescence activity of the cells by ARID1A knockdown, indicating the important role of ARID1A deficiency in the regulation of the replicative ability of the cancer cells." (PMID 35069887, 2022). "In 2013, a new molecular classification of EC profiling shed light on four different EC genomic subtypes, detecting high frequencies of somatic mutations in well‐known cancer genes such as ARID1A (33%)." (PMID 35167193, 2022). "As the most frequently mutated chromatin regulator across all cancers, it is important to note the role of ARID1A in global transcription regulation." (PMID 35626165, 2022). "Mutations in the ARID1A gene have been found in various cancers, but are particularly frequent in CCOC and ENOC, as well as in endometroid and clear-cell endometrial cancers." (PMID 36612107, 2022). "Elucidating the downstream signaling pathways in cells with KO of AXIN1 and/or ARID1A would be necessary to define the underlying molecular mechanisms regulating their effect on cancer cell proliferation and migration." (PMID 35669430, 2022). "We showed that ARID1A-deficient cancer cells developed a high susceptibility to PARP inhibitors in the presence of TMZ and link BER and TLS functionally." (PMID 36123603, 2022). "The same group of authors showed that somatic mutations of PIK3CA were detected in 17 (40%) tumors, and the majority (71%) of these were ARID1A-deficient carcinomas." (PMID 35457244, 2022). "Consistent with its related roles in oncogenesis, EP300 is mutated at high rates in several cancers that are also associated with ARID1A loss, including basal cell (23%), bladder (15%), and uterine (15%) carcinomas." (PMID 34731603, 2021). "APR-246, a glutathione inhibitor, can act as an effective agent to induce synthetic lethality in ARID1A-deficient cancer cells." (PMID 33525614, 2021). "A recent study shows that ARID1B is a specific vulnerability in ARID1A mutant cancers, further highlighting the potential of synthetic lethal strategies for ARID1A mutation in cancer." (PMID 34671561, 2021). "ARID1A mutation is a biomarker for immune checkpoint blockade therapy in several types of cancers, and it shapes cancer immune phenotype by dMMR and defining cancer interferon responsiveness and immune evasion." (PMID 34177954, 2021). "In particular, in histological or molecular subtypes of cancer, ARID1A mutations usually occur with high specificity." (PMID 34671561, 2021). "ARID1A mutation is prevalent in cancers, and synthetic lethal therapies associated with these mutations are being actively explored." (PMID 34737943, 2021). "Intriguingly, the R1989* nonsense mutation in the DUF3518 domain in ARID1A has been identified in various human cancers." (PMID 34671561, 2021). "In line with this, the therapeutic potential of EZH2 inhibitors against ARID1A-deficient cancers has been demonstrated." (PMID 33917230, 2021). "ARID1A mutations are specific in cancers of different tissue subtypes, which is due to the variations in mutation-corresponding mechanisms." (PMID 34671561, 2021). "These broad and complex effects make it challenging to identify the driving mechanisms of ARID1A deficiency in promoting cancer progression." (PMID 33983114, 2021). "A higher level of DSBs and cell death, demonstrated by immunoreactivity for phosphor-H2AX and cleaved caspase-3 respectively, was found in ARID1A-deficient cancers after combined radiation and PARP inhibitor therapy." (PMID 34737943, 2021).
cancer (continued). "Another study also confirmed that the inhibition of ATM/Chk2 DNA damage checkpoint axis would exhibit anti-cancer efficacy only in ARID1A-mutated cancer cells." (PMID 34715776, 2021). "In particular, several pan-cancer genome-wide studies repeatedly identified ARID1A as one of the top 10 most frequently mutated genes." (PMID 33917230, 2021). "By far, ARID1A mutation has been found in cooperation with several processes associated with cancer development and progression, including the PI3K/AKT pathway, cell cycle arrest, hormone signaling regulation, and MMR deficiency." (PMID 34671561, 2021). "Members of the SWI/SNF complex, most notably ARID1A/B, are among the most frequently mutated targets in all human cancers, including NB, resulting in a poor clinical outcome." (PMID 33404859, 2021). "In many cancers, mutation of ARID1A has been found to co-occur with mutations in the PI3K/AKT pathway, among which the coexistence of ARID1A deficiency and phosphatidylinositol 3-hydroxy kinase (PIK3CA) mutation is a more typical phenomena." (PMID 34671561, 2021). "Together this work extends mechanisms of replication stress in ARID1A deficient cells with implications for targeting ARID1A deficient cancers." (PMID 33826602, 2021). "As has been found for several other SWI/SNF complex components, loss-of-function mutations in ARID1A have been discovered in various cancers." (PMID 34050264, 2021). "ARID1A mutations are associated with a wide range of cancers, including ovarian endometrioid/clear-cell carcinomas, pancreatic cancer, gastric carcinoma, esophageal adenocarcinoma, renal carcinoma and breast tumors." (PMID 33748136, 2021). "ARID1A is identified as a tumor suppressor gene and is mutated at a high frequency in diverse cancers, such as ovarian clear cell carcinoma (∼57%), uterine corpus endometrial carcinoma (∼30%), and stomach adenocarcinoma (∼31%)." (PMID 34805154, 2021). "It has been established that tumors formed by ARID1A-deficient cancer cells exhibited elevated PDL1 expression." (PMID 34924820, 2021). "The AT-rich interaction domain 1A (ARID1A) is the most frequently mutated SWI/SNF gene across a broad spectrum of human cancers, which facilitates access of proteins to DNA." (PMID 34249744, 2021). "Targets above would provided us with more options for the treatment of ARID1A-mutated cancer but requires further studies." (PMID 34715776, 2021). "ARID1A mutations specifically promote cancer cells to invade nearby tissue, a hallmark of metastasis, associated with squamous differentiation." (PMID 34941867, 2021). "Numerous somatic mutations, including cancer-associated mutations in ARID1A, ATM, CDH4, NRAS, and PIK3CA, were shared among the epithelium from the uterine endometrium, endometriotic lesions distant from and adjacent to the carcinoma, and the carcinoma itself." (PMID 33809880, 2021). "PI3K/AKT pathway inhibitors, such as the AKT inhibitor MK2206 and PI3K inhibitors LY294002 and BKM120, have been demonstrated to be effective to inhibit proliferation and growth in ARID1A-loss cancer cells." (PMID 34671561, 2021). "The ARID1A tumor suppressor gene, a commonly found mutation across cancers, has also showed its potential in endometrial carcinogenesis by integrating with PTEN inactivation." (PMID 34036097, 2021). "ARID1A alterations promote cancer iper-mutated phenotype and co-occurring specific genetic mutations in cancers with ARID1A alterations are detected." (PMID 33315149, 2021). "Recent studies had uncovered the potential role of ARID1A alterations or expression loss in the therapeutic sensitivity of cancers, but the studies in this field requires to be further summarized and discussed." (PMID 34715776, 2021). "Mutation of ARID1A has been documented in a number of cancers, and approximately 8% of lung ADCs contain mutations in ARID1A." (PMID 33407425, 2021).